IGF2BP1 (insulin like growth factor 2 mRNA binding protein 1)
Diseases named in the same sentence as IGF2BP1 in open-access papers (continued):
Sharing a sentence is not in itself a finding about the gene and the disease.
tumor (continued). "The let-7 family exerts its role in suppressing the migration and growth of tumor cells by inhibiting the expression of IGF2BP1." (PMID 34416861, 2021). "(C–E) The relationships between the IGF2BP1 protein and tumor size (C), TNM stage (D), and differentiation (E) were determined." (PMID 34779401, 2021). "IGF2BP1 promoted mesenchymal-like cell properties in tumor-derived cells, and was experimentally proved to serve as a pro-mesenchymal factor." (PMID 32272940, 2020). "Protein levels of Gli1, Myc, and IGF2 were significantly downregulated as well in LIN28B-AS1 KO tumor tissues, with IGF2BP1 protein levels unchanged." (PMID 32917856, 2020). "The IGF2 mRNA-binding protein 1 (IGF2BP1) promotes the proliferation and in vivo growth of tumor cells derived from a variety of solid cancers." (PMID 32761127, 2020). "Unexpectedly, IGF2BP1 has also been correlated with a tumour‐suppressive role in breast cancer and gallbladder carcinoma, suggesting the existence of a cell‐specific post‐transcriptional regulation." (PMID 33391635, 2020). "Mechanistically, TRPM2-AS serves as a microRNA sponge or a competitive endogenous RNA (ceRNA) for tumor suppressive microRNA miR-612 and consequently modulates the derepression of IGF2BP1 and FOXM1." (PMID 32123162, 2020). "BTYNB was shown to impair the association of IGF2BP1 with the MYC RNA in vitro and 2D proliferation of various tumor cells." (PMID 32761127, 2020). "In contrast, these findings indicated a pivotal role of IGF2BP1 in regulating E2F-driven transcription in a concise manner across different cancers and tumor cell lines." (PMID 32761127, 2020). "After transcription, IGF2BP1 can correct the mRNA expression of certain oncogenes, thereby promoting tumor cell proliferation and growth, invasion and chemical metabolism, which is related to a poor overall survival and metastasis of various cancers." (PMID 32653017, 2020). "This indicated, IGF2BP1 is a conserved regulator of G1/S-transition in cancer cells, controlling tumor cell proliferation in vitro and tumor growth in vivo." (PMID 32761127, 2020). "This indicated the importance of the IGF2BP1’s RNA-binding capacity in controlling tumor cell proliferation and spheroid growth." (PMID 32761127, 2020). "The loss of SIRT6 in PDAC tumor models was associated with upregulation of LIN28B and consequently increased expression of the let-7 targets HMGA2, IGF2BP1, and IGF2BP3." (PMID 32545414, 2020). "Though IGF2BP1 is annotated as a tumour driver, its role in promoting chemoresistance of tumour cells remains poorly understood." (PMID 32857912, 2020). "Expression of IGF2BP1 has been reported in a panel of human tumours, and substantial data have shown that IGF2BP1 drives tumorigenesis both in vitro and in vivo." (PMID 32857912, 2020). "IGF2BP1 is a post-transcriptional regulator that affects the stability, translatability, and localization of essential mRNAs involved in tumor cell proliferation, growth, and invasion." (PMID 33287884, 2020). "A tumor-suppressive function is exerted by IGF2BP1 too, which inhibits KRAS, CDC34, and MYC expression and promotes apoptosis." (PMID 33238574, 2020). "SRF-dependent transcriptional regulation is a key modulator of cytoskeletal dynamics and was shown to promote tumor cell invasion and experimental metastasis, as recently shown for IGF2BP1 in EOC-derived cells." (PMID 30371874, 2019). "How IGF2BP1 or SRF influence tumor cell viability at low adhesion and mitogen stimulation (FBS, 1%) was analyzed by anoikis resistance assays upon depleting both factors in ES-2 cells." (PMID 30371874, 2019). "The conserved phenotypic role of IGF2BP1 in tumor-derived cells suggests that the protein, in addition to promoting MYC synthesis, enhances additional oncogenic pathways not or barely affected by the other IGF2BP homologs." (PMID 30371874, 2019).
tumor (continued). "In part, variable effects on gene expression were expected since IGF2BP1 controls target mRNA abundance in a miRNome-dependent manner, and miRNA expression (the miRNome) varies between distinct tumor cell lines." (PMID 30371874, 2019). "Recent studies indicate that IGF2BP1 has the most conserved ‘oncogenic’ role of the IGF2BP family in tumor-derived cells." (PMID 30371874, 2019). "Growing evidence indicates that CDH17 and IGF2BP1 are related to cell proliferation and tumor metastasis." (PMID 31427725, 2019). "This revealed that IGF2BP1 also serves SRF-independent roles in cancer cells and thus supports the notion that IGF2BP1 promotes an ‘aggressive’ tumor cell phenotype via pleiotropic effectors." (PMID 30371874, 2019). "The reasonable inferences about the functions of IGF2BP1 in cancer biology can be confirmed in the future by in vivo and in vitro studies, according to specific origins or conditions of the tumor cells." (PMID 29954406, 2018). "Taken together, we can deduce a conclusion that IGF2BP1 plays an important role in the occurrence of tumor events and shows a degree of tumor suppressor effect." (PMID 29954406, 2018). "Although the expression levels of PTGS2, ACTB, and MAPK4 are reduced by IGF2BP1 interfering with their mRNA translation, there are different results on tumor events." (PMID 29954406, 2018). "In a mouse model, upregulation of miR-491-5p was observed to enhance the tumor cell cycle arrest at the G1/G0 stage and promote tumor cell apoptosis, as well as repress tumor cell proliferation, migration, and invasion, and growth by inhibiting IGF2BP1." (PMID 29954406, 2018). "In most of the cancers, IGF2BP1 enhances tumor cell proliferation, survival, adhesion-independent growth and invasion, and chemo-resistance." (PMID 29954406, 2018). "IGF2BP1 overexpression was showed to significantly associate with younger onset age in LUSC and bigger tumor size and poor overall survival in LUAD." (PMID 29954406, 2018). "The let-7 miRNA family was dysregulated in various cancers, including OC, and had a tumor-suppressive role by interfering in the expression of multiple oncogenic factors, including IGF2BP1." (PMID 29954406, 2018). "Some miRNAs including miR-506 and miR-873 were showed to be lowly expressed in GBM tissues or cells and play a tumor-suppressive role in this disease by targeting and modulating IGF2BP1." (PMID 29954406, 2018). "IGF2BP1 was demonstrated to play tumor-suppressive or tumorigenic roles in gastrointestinal cancers." (PMID 29954406, 2018). "In both hepatocellular carcinoma and glioblastoma cell lines, downregulating IGF2BP1 via different microRNAs reduces tumor proliferation and invasion potential." (PMID 30558204, 2018). "By regulating those mRNAs, IGF2BP1 has been identified to play important roles in cell proliferation and growth of normal tissues and tumor tissues, as well as tumor cell adhesion, apoptosis, migration, and invasion." (PMID 29954406, 2018). "Five of these recurrently deleted miRs targeted the insulin-like growth factor 2 mRNA-binding protein 1 (IGF2BP1) gene product, and a correlating 100-fold upregulation of IGF2BP1 mRNA was seen in tumor specimens." (PMID 28486549, 2017). "The mRNA binding protein IGF2BP1 promotes EMT while its knockdown reduces cell migration in various mesenchymal-like tumor cells." (PMID 27144453, 2016). "IGF2BP1 has been shown to be involved in tumor development by targeting mRNAs such as IGF2 and c-myc." (PMID 25889892, 2015). "Among several functional activities, IGF2BP1 binds mRNAs, prevents miRNA-mediated repression and regulates tumor progression." (PMID 25889892, 2015). "Mechanically, miR-9 plays a tumor suppressive role partially through a functional miR-9/IGF2BP1/AKT&ERK axis." (PMID 26547929, 2015). "Intriguingly, higher IGF2BP1 mRNA level in tumor was positively correlated with higher level of α-fetoprotein (AFP), the most widely used diagnostic biomarker for HCC (P = 0.029)." (PMID 26547929, 2015).
tumor (continued). "The newly identified miR-9/IGF2BP1/AKT&ERK axis represents one of the anti-tumor mechanisms of miR-9 in HCC." (PMID 26547929, 2015). "Downregulation of let-7 expression, frequently observed in aggressive tumor cells, was correlated with increased drug-resistance and an upregulation of IGF2BP1." (PMID 23069990, 2013). "Consistent with various in silico-predicted poly-adenylation sites in the approximately 7-kb-long 3′-UTR of the transcript, at least three IGF2BP1 transcripts were observed in various tumor-derived cells and HEK293 cells." (PMID 23069990, 2013). "The oncofetal IGF2 mRNA-binding protein 1 (IGF2BP1) controls the migration and invasiveness of primary as well as tumor-derived cells in vitro." (PMID 23677615, 2013). "This study identifies a novel mechanism by which the RBP IGF2BP1 sustains mesenchymal tumor cell properties and promotes the migration of tumor-derived cells in vitro." (PMID 23677615, 2013). "In agreement with this, we have observed that the forced expression of IGF2BP1 promoted the invasiveness of tumor cells in vitro, whereas the opposite was observed upon its knockdown (unpublished)." (PMID 23069990, 2013). "In previous studies, we demonstrated that IGF2BP1 promotes the migratory potential as well as cell-matrix contact formation of various tumor-derived cells." (PMID 23677615, 2013). "Taken together, this indicated that IGF2BP1 rather sustains than induces mesenchymal-like cell properties in tumor-derived or immortalized cells." (PMID 23677615, 2013). "These pro-epithelial changes in cell morphology and marker expression were observed to varying extend for all analyzed tumor-derived cells expressing IGF2BP1." (PMID 23677615, 2013). "Like in primary neurons, IGF2BP1 also serves essential roles in regulating actin dynamics in tumor-derived cells." (PMID 23677615, 2013). "In agreement with this pro-mesenchymal role of IGF2BP1, the protein is predominantly observed in mesenchymal-like tumor-derived cells in which it enhances motility." (PMID 23677615, 2013). "Strikingly, we observed that IGF2BP1-facilitated modulation of tumor cell migration involves IGF2BP1-directed control of LEF1 and SNAI2 expression." (PMID 23677615, 2013). "This supports the view that IGF2BP1 enhances tumor cell aggressiveness, since the let-7 microRNA family is considered to facilitate a tumor-suppressive role in most malignancies." (PMID 23069990, 2013). "In this study, we reveal that IGF2BP1 enhances mesenchymal-like cell properties in tumor-derived cells by promoting the expression of the transcriptional regulators LEF1 and SLUG (SNAI2)." (PMID 23677615, 2013). "Despite this strong evidence indicating an essential role of IGF2BPs in the modulation of chemotactic movement, IGF2BP1 apparently also serves a role in controlling the random migration of tumor-derived cells." (PMID 23069990, 2013). "Accordingly, we propose that IGF2BP1 is a pro-mesenchymal marker that sustains mesenchymal-like cell properties and promotes migration of tumor-derived cells in a largely context-independent manner." (PMID 23677615, 2013). "This supported the view that IGF2BP1 serves an essential pro-mesenchymal role in tumor-derived cells, suggesting the protein as a mesenchymal marker." (PMID 23677615, 2013). "The observed post-transcriptional control of IGF2BP1 expression by microRNAs was suggested to modulate tumor cell fate." (PMID 23069990, 2013). "Our recent studies indicate that IGF2BP1 promotes the velocity of tumor cell migration and migration-supportive adhesion by limiting MAPK4 mRNA translation and consequently MK5-directed phosphorylation of HSP27." (PMID 23069990, 2013). "m6A-modulated mRNA stability, particularly via IGF2BP1, regulates the expression of RRM2 and thrombospondin 1 (THBS1), contributing to resistance against ferroptosis and the glycolytic reprogramming of tumor-associated macrophages, ultimately promoting tumor progression and fibrosis." (PMID 41376856, 2026).
tumor (continued). "Studies have found that IGF2BP1 can alter the TME by stabilizing tumor-related mRNAs." (PMID 40584294, 2025). "Despite strong evidence supporting their role as oncogenes and influencing tumor cells aspects such as self-renewal, apoptosis, metabolic reprogramming, and immune evasion, recent studies have found that IGF2BP1 plays a tumor-suppressive role in various tumors." (PMID 40088376, 2025). "In addition, the deletion of IGF2BP1 in HCC-derived HepG2 cells inhibited the tumor growth during the Xenograft studies." (PMID 39674501, 2025). "Overall, the increase in IGF2BP1/2/3 expression might be accompanied by the infiltration of stromal cells and immune cells in the tumor immune microenvironment." (PMID 40088376, 2025). "Additionally, IGF2BP2 is widely expressed in both normal and tumor tissues, while IGF2BP1 and IGF2BP3 are overexpressed in many malignant tumors and are considered oncofetal proteins." (PMID 40088376, 2025). "IGF2BP1 affects programmed cell death by reducing CD8+ T cell‐mediated tumor cytotoxicity." (PMID 39802639, 2025). "As proof of concept that AVJ16 could be a useful tool in a clinically relevant setting, we compared the response to AVJ16 treatment of a human healthy lung organoid versus a human NSCLC organoid from a surgically resected tumor that expresses IGF2BP1." (PMID 40629079, 2025). "Hence, IGF2BP1 serves as a critical mediator for sustained tumor cell proliferation by regulating multiple growth signal pathways." (PMID 40584294, 2025). "Its role in these metabolic pathways makes IGF2BP1 a significant factor in tumor progression." (PMID 40584294, 2025). "In contrast, Igf2bp1 loss only modestly reduced tumor growth in Foxn1nu mice, likely reflecting the pro-proliferative role of IGF2BP1 and the absence of immune-mediated pressure in this model." (PMID 41444249, 2025). "The expression levels of IGF2BP1/2/3 varied between tumor tissues and adjacent normal tissues." (PMID 40088376, 2025). "Furthermore, alterations in the expression of IGF2BP1/2/3 can potentially activate or inhibit the immune checkpoints, thereby influencing anti-tumor response." (PMID 40088376, 2025). "Additionally, knocking down IGF2BP1 in colonic stromal cells promotes the tumor microenvironment and histological grading." (PMID 40088376, 2025). "Moreover, we discuss the prospects of IGF2BP1 as a potential tumor diagnosis marker, as well as a potential target for an anti-tumor therapeutic strategy." (PMID 40584294, 2025). "IGF2BP1 is also involved in tumor cell lipid metabolic reprogramming." (PMID 40584294, 2025). "In addition, we highlight the clinical significance of IGF2BP1 as a biomarker for tumor prognosis and a potential target for tumor therapy." (PMID 40584294, 2025). "IGF2BP1 is reported to be a critical regulator of stem cell features in various tumor types." (PMID 40584294, 2025). "Moreover, given that cell death resistance is a characteristic of tumor cells that contributes significantly to tumorigenesis, the negative regulation of IGF2BP1 on regulated cell death emphasizes the pivotal role of IGF2BP1 as an oncogene." (PMID 40584294, 2025). "This unexpected association implies that in specific molecular contexts, such as within Asian populations with EC, IGF2BP1 overexpression may trigger compensatory apoptotic mechanisms that attenuate tumor progression." (PMID 41210679, 2025). "While IGF2BP1 is generally characterized as an oncogenic RNA-binding protein that stabilizes m6A-modified transcripts to support tumor growth, its high expression in our cohort was independently associated with reduced levels of pSTAT3 and, notably, with improved overall survival." (PMID 41210679, 2025). "Thus, although further investigations are necessary, these facts point out the possible involvement of IGF2BP1 in tumor cell autophagy." (PMID 40584294, 2025).
tumor (continued). "Additionally, in certain tumors (BLCA and LUAD), IGF2BP1/2/3 expression was correlated with the tumor pathological stage and increased with advancing stage." (PMID 40088376, 2025). "LOC101928222 or HMGCS2 knockdown reduced tumor-initiating capacity of CRC cells in nude mice, overexpression of HMGCS2 or IGF2BP1 could rescue the tumor-initiating capacity of LOC101928222 or HMGCS2-knockdown CRC cells." (PMID 38965575, 2024). "We detected the expression of YTHDF1 or IGF2BP1 in normal epithelial and tumor cell lines." (PMID 39185313, 2024). "At the single-cell level, IGF2BP1 was predominantly expressed in malignant cells (cluster 0), with negligible expression observed in other cell types; consequently, we designated cluster 0 as RNA-modified tumor cells." (PMID 39512352, 2024). "IGF2BP1 enhances tumor growth by stabilizing mRNAs that code for cell cycle regulators." (PMID 39062749, 2024). "It has been confirmed that IGF2BP1 plays a dual role in tumor regulation." (PMID 39342091, 2024). "Similarly, HOXA5 and IGF2BP1 regulate gene expression, with IGF2BP1 enhancing tumor growth and metastasis by stabilizing mRNA." (PMID 39597836, 2024). "In the tumor tissue, the IGF2BP1 silencing reduced the PD-L1 level." (PMID 39606242, 2024). "Overall, the data suggest that IGF2BP1 protein can be considered to be a moderately tumor-enriched biomarker in EAC, but it may only be useful as a therapeutic target or diagnostic biomarker in a limited proportion of patients." (PMID 38604503, 2024). "Notably, IGF2BP1 promotes tumor occurrence and progression in an m6A-dependent manner, which is particularly remarkable." (PMID 39342091, 2024). "Considering this information, we propose the hypothesis that the downregulation of circFAM13B in MB may upregulate IGF2BP1 expression levels and, thus, promote tumor growth through deregulation of the MYC and FSCN1 oncogenes." (PMID 37835380, 2023). "However, i.t. treatment substantially impaired tumor growth, indicating strong target potential of IGF2BP1 and therapeutic lead prospects of BTYNB." (PMID 37246217, 2023). "Additionally, we illustrated the role of IGF2BP1 in BC clinical significance and infiltrating immune cells in the tumor microenvironment through bioinformatic analysis." (PMID 36966311, 2023). "However, it remains poorly understood how circRNAs interact with IGF2BP1 in regulating tumor immune evasion of NSCLC." (PMID 36672208, 2023). "Characterizing the global Igf2bp1 RNA binding changes (both down and up-regulated) that are induced by treatment with 7773 should provide insights into how the compound achieves its anti-tumour effects." (PMID 34895045, 2022). "The results suggest that IGF2BP1 may be used to predict the level of immune cell infiltration and tumor purity in cancer tissues and assist with chemotherapy drug selection in clinical practice." (PMID 36249006, 2022). "Remarkably, in this study IGF2BP1 mRNA was enriched 3-fold in lymph node and liver metastases compared to the primary tumor tissue, raising the hypothesis that IGF2BP1 could functionally contribute to the prometastatic phenotype leading to worsened prognosis." (PMID 35565249, 2022). "In several studies, an enhanced expression of IGF2BP proteins could be demonstrated in various tumor entities, with IGF2BP1 and IGF2BP3 showing bona-fide oncofetal, but distinguished expression patterns." (PMID 35565249, 2022). "IGF2BP1 is functionally considered to promote tumor growth and invasion via the transport of certain mRNAs that play essential roles in embryogenesis, carcinogenesis, and chemo-resistance by affecting mRNA stability, translatability, or localization within most cancers." (PMID 36092925, 2022). "IGF2BP1 is involved in the proliferation, adhesion, and migration in tumor development." (PMID 35935853, 2022).